IL6 (interleukin 6)
Diseases named in the same sentence as IL6 in open-access papers (continued):
Sharing a sentence is not in itself a finding about the gene and the disease.
metabolic syndrome (continued). "The present meta-analysis revealed that flaxseed consumption had an overall beneficial effect on serum TC, LDL-C, TG, apo B and IL-6 in patients with dyslipidemia related diseases, but not on apo A, HDL-C, hs-CRP, CRP and anthropometric indices." (PMID 34635132, 2021). "Furthermore, systemic inflammation, indicated by serum TNF-α and IL-6 levels, was also decreased by CCL4 inhibition in type 2 DM and metabolic syndrome mouse models in this study." (PMID 33968046, 2021). "Both psoriasis and metabolic syndrome (MetS) are characterised by an inflammatory T cell-mediated process, with over-expression of pro-inflammatory cytokines, tumour necrosis factor (TNF)-a, and interleukin (IL)-6." (PMID 32550048, 2020). "Indeed, elevated pro-inflammatory cytokines such as C-reactive protein (CRP), interleukin (IL)-6, including lipid peroxidation makers, such as malondialdehyde (MDA) levels, have been identified in patients with dyslipidemia." (PMID 32375340, 2020). "Metabolic syndrome leads to a higher secretion of inflammatory mediators, such as leptin, tumor necrosis factor alpha (TNF-α), monocyte chemoattractant protein-1 (MCP-1), resistin, and interleukin 6 (IL-6)." (PMID 33123088, 2020). "Also, the results of the present study suggested that nano-curcumin supplementation significantly decreases serum concentrations of TNF-a, IL-6, MDA, and hs-CRP in subjects with metabolic syndrome." (PMID 32256716, 2020). "Our CVD nomogram has 5 components: age, IL-6 and APN levels, DBP, and dyslipidemia, with a predictive ability higher than that of the Framingham study (AUC approximately 0.80) and the simple model for a 10-year risk assessment program for ischemic cardiovascular disease in Chinese (AUC = 0.796)." (PMID 31191115, 2019). "Therefore, we have decided to search for the relationship between the TNFα gene polymorphisms and serum levels of proinflammatory cytokines (IL-1α, IL-1β, IL-6, TNFα, IFNγ) and CRP in women with metabolic syndrome." (PMID 30383538, 2018). "In treated patients the dyslipidemia correlates better with C-reactive protein and IL-6 levels, rather than with CD4 count or HIV viral load, suggesting that immune activation has a central role in the development of dyslipidemia." (PMID 30233499, 2018). "Significant associations between the identified TAG species and traits of metabolic syndrome such as age, BMI, lipids (total cholesterol and circulating TAG), the inflammatory marker IL-6 and adipogenic capacity of preadipocytes derived from the same adipose tissues were identified." (PMID 29940972, 2018). "For example, a three month intervention study reported that a very low-carbohydrate diet (12% of energy from carbohydrates daily) resulted in more reduction in IL-6, IL-8, and TNF-alpha concentrations than did in a low-fat diet (25% fat, with 10% saturated fat) in 40 young adults with dyslipidemias." (PMID 26393645, 2015). "Epidemiological studies have demonstrated an increase in plasma levels of inflammatory markers such as C-reactive protein (CRP), interleukin-6 (IL-6) and tumour necrosis factor-α (TNF-α) in patients with metabolic syndrome (MetS) and also in those with clinically overt Type 2 DM." (PMID 25276234, 2014). "In the current study, CRP and IL-6 levels measured three years later in the same cohort were also higher in patients with metabolic syndrome but did not pass cutoffs for statistical significance (p<0.08 for CRP and p<0.13 for IL-6)." (PMID 22701684, 2012). "The aim of this study is to establish interactions between the GLP-1 plasma levels and metabolic syndrome clusters and adipokines profile (leptin, adiponectin, resistin) and proinflammatory cytokines (TNFα, IL-6, IL1β, IL-17) in diabetic subjects with or without MAFLD." (PMID 41683648, 2026). "Moreover, IL-6 levels were not changed by low-energy cranberry juice (daily, 8 weeks) in women with metabolic syndrome." (PMID 40944222, 2025).
metabolic syndrome (continued). "Diets high in saturated fats and sugars have been shown to lead to dyslipidemia by increasing TG and decreasing HDL-C levels, thereby promoting an atherogenic lipid profile, which is often accompanied by elevated inflammatory markers such as C-reactive protein (CRP) and interleukin-6 (IL-6)." (PMID 40077646, 2025). "However, higher levels of IL-6 and TNF-α were associated with the Framingham Risk Score, whereas hsCRP and metabolic syndrome were not." (PMID 40713717, 2025). "Additionally, future research should consider adipose tissue parameters alongside other clinical variables—such as metabolic syndrome components, systemic inflammatory markers (e.g., CRP, IL-6), and genetic or epigenetic factors—to develop comprehensive, multifactorial risk prediction models." (PMID 40868344, 2025). "Nevertheless, rs1800629 has been previously reported to modulate the expression of key components within the inflammatory signaling cascade, which could influence the production of pro-inflammatory cytokines such as IL-6, TNF-α, IFN-γ, particularly in patients with metabolic syndrome." (PMID 40881695, 2025). "Moreover, persistent high levels of IL-6 also promoted fat breakdown, release of free fatty acids, and synthesis of very low-density lipoprotein (VLDL) in the liver, further exacerbating dyslipidemia and systemic metabolic disorders, thereby significantly increasing the risk of MS." (PMID 41450839, 2025). "In the broader context of chronic diseases, dyslipidemia promotes the recruitment of inflammatory cells, such as macrophages, to affected tissues, where they release pro-inflammatory cytokines and chemokines, including TNF-α, IL-1β, IL-6, IL-8, MCP-1, VEGF, and adhesion molecules." (PMID 39457689, 2024). "In another study, TNF-α and IL-6 concentrations and myeloperoxidase activity were higher (whereas catalase and superoxide dismutase activities were lower) in consumers with a high intake of ultra-processed food (UPF) with metabolic syndrome than in those with a low intake of UPF." (PMID 38542788, 2024). "This could be due to dyslipidemia’s negative impact on the immune system, such as activation of inflammasomes, overproduction of the pro-inflammatory cytokine interleukin-6, and reduction in serum immunoglobulin levels." (PMID 37242357, 2023). "Rats with dyslipidemia (D group) presented higher tissue levels of evaluated cytokines compared to the C group (p ≤ 0.020), but when compared to the H group, IL-1β, and IL-6 were not significantly different (p > 0.25)." (PMID 35163364, 2022). "And it was also indicated that SUA might take part in stimulating the secretion of inflammatory markers such as C-reactive protein (CRP), interleukin (IL)-6, IL-18, and tumor necrosis factor (TNF)-alpha which are crucial to the development of metabolic syndrome." (PMID 35673358, 2022). "Furthermore, there were significant differences between before and after subgroup analyses in the stratum of metabolic syndrome for TNF-α (SMD = − 1.42; 95% CI − 3.38, 0.55; p > 0.05) and the stratum of cardiovascular disease for IL-6 (SMD = − 0.42; 95% CI − 1.24, 0.39; p > 0.05)." (PMID 35352233, 2022). "Adipose tissue can synthesize and secrete important adipose cytokines such as LP, TNF-α, IL-6, and ADP; participate in the regulation of glucose metabolism, lipid metabolism, and inflammation; and play a key role in the occurrence and development of metabolic syndrome." (PMID 34422044, 2021). "Similarly, the FA quality of high-fat meals did not elicit differences in postprandial IL-6 concentrations in metabolic syndrome patients or obese and lean women." (PMID 33758921, 2021). "Thus, in patients with metabolic syndrome, vitamin D therapy resulted in significant IL-6 reduction but did not change CRP concentration." (PMID 32825324, 2020). "Also, we found a significant reduction of IL-6 and CRP in women with metabolic syndrome." (PMID 32256716, 2020).
metabolic syndrome (continued). "The increasing trend of IL-6 and Il-1β can be explained by antipsychotics (especially atypical antipsychotics) side effects such as metabolic syndrome in the long period, as increased levels of IL-6, IL-1β, TNF-α, IL-2, IFN-γ, and IL-4 have been reported in patients with metabolic syndrome." (PMID 31908647, 2019). "It is therefore important to determine whether IL-6 or IL-1β mediates adipose tissue metaflammation during macrophage infiltration via modulating MAPK or NF-κB pathway, to help further elucidate the pathophysiology of metabolic syndrome." (PMID 30697360, 2019). "Furthermore, combined use of ghrelin and inflammatory markers (IL-6, CRP) failed to explain the association between the metabolic syndrome and the cardiovascular mortality in older adults." (PMID 28100170, 2017). "Epidemiological data have indicated that subjects with dyslipidemia are in a proinflammatory state, which is distinguished by elevated levels of cytokines, such as tumor necrosis factor-alpha (TNF-α) and IL-6 and could further promote the expression of hsCRP and CAMs." (PMID 24558466, 2014). "It has indeed been demonstrated in numerous studies that HS and metabolic syndrome (MetS) share a core link through meta-inflammation, driven by common pro-inflammatory cytokines, such as tumor necrosis factor (TNF)-α, interleukin (IL)-1β and IL-6." (PMID 42266681, 2026). "Metabolic syndrome (MetS) is defined as a state of low-grade chronic inflammation, evidenced by elevated serum levels of pro-inflammatory cytokines like tumor necrosis factor alpha (TNF-α) and interleukin-6 (IL-6)." (PMID 41590667, 2026). "In conclusion, our results suggest that SH-HCC is a distinctive variant of HCC, which develops more frequently in metabolic syndrome patients, and that senescent and damaged CAFs, as well as non-tumoral stellate cells with SASP, including IL-6 expression, may contribute to the development of SH-HCC." (PMID 28273155, 2017). "However, in a study of human subjects with metabolic syndrome, 60-day supplementation with cranberry juice did not cause significant changes in the levels of pro-inflammatory cytokines: TNF-alpha, IL-1 and IL-6, despite an improvement of some cardiovascular risk factors." (PMID 28261001, 2017). "After more than two years of follow-up, it was shown that MTX did not produce lower levels of IL-1β, IL-6, CRP, or components of the metabolic syndrome than the placebo." (PMID 41155215, 2025). "Although the clinical significance of these associations may be low, as dyslipidemia secondary to TCZ treatment has not been linked to an increased risk of cardiovascular events, the interplay between lipid profiles and inflammatory pathways, such as IL-6, has been extensively described." (PMID 38001504, 2023). "From this perspective, the absence of differences in the levels of IL-6 and TNF-α among the studied groups can be explained by the crossover effects of the presence of schizophrenia and metabolic syndrome." (PMID 33066473, 2020). "Inflammation has been shown to be associated with metabolic syndrome, and oral cancer patients with metabolic syndrome had higher inflammation status than those without metabolic syndrome (data not shown, hs-CRP, p = 0.02; IL-6, p = 0.01)." (PMID 32293339, 2020). "Chedraut and colleagues found that cytokine levels (IL-6 and TNF-α) did not correlate with hot flash scores of the menopause-specific quality of life questionnaire in postmenopausal women with metabolic syndrome." (PMID 28846735, 2017). "vWF and TNF-α compared to subjects without metabolic syndrome; in CEI group with metabolic syndrome IL-6, TNF-α and v-WF were more positively and significantly related to AIx compared to subjects without metabolic syndrome." (PMID 24571954, 2014).
metabolic syndrome (continued). "While prior studies have focused on tear cytokines in diabetic retinopathy, our study identified elevated tear cytokines (IL-6, CXCL8, IL-15, CCL5, and VEGF) in diabetic patients without diagnosed retinopathy, persisting after controlling for age, hypertension, and dyslipidemia." (PMID 41030257, 2025). "Similarly, cranberry juice (700 mL/day for 60 days) in patients with metabolic syndrome reduced lipid peroxidation and protein oxidation levels but did not reduce TNF-α, IL-1, and IL-6." (PMID 38752013, 2024). "TNF-α, IL-6, and CPR more strongly correlated with arterial stiffness parameters in patients with ischemic stroke and metabolic syndrome compared to those with acute ischemic stroke but without metabolic syndrome." (PMID 34202323, 2021). "In patients with acute ischemic stroke and metabolic syndrome, measures of arterial stiffness (carotid–femoral PWV and aortic augmentation index) and inflammatory cytokines (TNF-α and IL-6), along with CRP, were increased compared to patients with acute ischemic stroke without metabolic syndrome." (PMID 34202323, 2021). "As an example, in healthy adults, the consumption of PS-enriched soy milk reduced lipid peroxidation and inflammatory markers, whereas in individuals with metabolic syndrome the PS treatment did not affect inflammatory biomarkers such as CRP, VCAM, ICAM, IL-6, CD40 ligand, E-selectin, and MCP-1." (PMID 32455866, 2020). "Thus, hyperinsulinemia and fasting insulin hypersecretion abated, dyslipidemia reversed, and the circulating concentrations of MCP-1 and IL-6 (but not TNFα) decreased." (PMID 28827671, 2017).
Hypertension (839 papers, 2005 to 2026). The presence of chronic increased pressure in the systemic arterial system. "Hypertension has been linked to higher levels of IL-6 and TNF-α, making the CNS more susceptible to neuroinflammatory injury." (PMID 39861166, 2025). "Il6 and miR-192, which are known to be associated with SS hypertension, were among them for the male group." (PMID 40232853, 2025). "The research also found that the positive association between IL-6 and the risk of hypertension became insignificant after adjustment for BMI." (PMID 40002786, 2025). "Hypertension is strongly associated with increased circulating levels of proinflammatory cytokines such as IL‐1β, IL‐6, and TNF‐α." (PMID 40454610, 2025). "A well-characterized inflammatory cytokine implicated in both renal disease, hypertension, and oxidative stress is IL-6." (PMID 40508164, 2025). "Elevated IL-6 levels are further implicated in promoting hypertension and renal fibrosis in CKD, with angiotensin II serving as a potent inducer of IL-6 production." (PMID 40570958, 2025). "Elevated renal IL-6 is consistently linked to increased renal injury in both induced and genetic rodent models of hypertension." (PMID 41184958, 2025). "In univariate analysis, the following factors were associated with APE development: older age, hypertension, pre-existing heart failure, high IL-6, NT-proBNP, and troponin levels." (PMID 41303223, 2025). "IL-6 single nucleotide polymorphisms have been linked with putative roles in subclinical inflammation, hypertension, and the development of type 2 DM." (PMID 38707766, 2024). "They discovered that elevated levels of hs-CRP and IL-6 were linked to a higher risk of hypertension." (PMID 38292866, 2024). "Increased serum levels of C-reactive protein (CRP) and interleukin-6 (IL-6) are associated with high blood pressure and an increased risk of hypertension." (PMID 38720047, 2024). "Inflammation markers, IL6 and TNFα, were found to be independent risk factors for hypertension in both normo- and prehypertensive subjects." (PMID 39558500, 2024). "IL6 promotes smooth muscle cell proliferation and is implicated in hypertension through interactions with cytokines." (PMID 38496269, 2024). "In persons with fatty livers, elevated pro-inflammatory cytokines (e.g., TNF-α, IL-6) compromise arterial endothelial function, hence heightening the risk of hypertension." (PMID 39598120, 2024). "IL-1β plasma level was positively associated with hypertension, whereas the circulating level of IL-6 was positively correlated with the age in CABG cohort." (PMID 37745103, 2023). "A study on subjects with pulmonary arterial hypertension (PAH) in China suggests that −572C/G promoter polymorphism in the interleukin-6 (IL-6) gene is associated with serum IL-6 levels and risk of hypertension." (PMID 37201134, 2023). "The specific mechanisms underlying hypertension and anxiety were subsequently discussed, including interleukin (IL)-6 (IL-6), IL-17, reactive oxygen species (ROS), and gut dysbiosis." (PMID 37273529, 2023). "Second, reducing SCFAs leads to an increase in proinflammatory cytokines, including TGF-β1, TNF-α, IL-1β, and IL-6, which in turn causes a reduction in glomerular filtration rate and consequently results in hypertension." (PMID 37273529, 2023). "In fact, some genetic association studies also have investigated the role of IL-6 polymorphisms in the development of hypertension individually, but the previous findings are inconsistent." (PMID 37920615, 2023). "When it comes to clinical studies, less consistent results were found in the association between IL-6 levels and the risk of hypertension." (PMID 37920615, 2023). "Our findings provide evidence that the IL-6 -174C > G polymorphism can affect its gene expression levels and risk of hypertension." (PMID 37920615, 2023).